CFB (complement factor B)
Diseases named in the same sentence as CFB in open-access papers (continued):
Sharing a sentence is not in itself a finding about the gene and the disease.
infection (48 papers, 2012 to 2026). The state of being infected such as from the introduction of a foreign agent such as serum, vaccine, antigenic substance or organism. "Two months post-infection, CFB, C3, C3aR, and C5aR1 expression remained higher than in controls, while CFP upregulation was transient." (PMID 33613523, 2020). "Complement factor B (CFB) an acute phase plasma protein is central to the action of the innate immune system in response to inflammation and infection and plays a role in B-cell activation and the cytotoxic reaction." (PMID 29470489, 2018). "Complement factor B and properdin can facilitate the generation of C3 convertase and activate the complement alternative pathway, which is the first line of defense against pathogen infection." (PMID 39335272, 2024). "Both stromelysin-1 and complement factor B were up-regulated at 42-days post-infection." (PMID 36227939, 2022). "Similar to BoLA production, increased CFB expression in Treated 2+ cattle on D0 may be due to disease at the time of arrival and a non-specific innate immune response to pathogenic infection." (PMID 39346910, 2024). "Sixteen cattle complement genes, including complement C2, complement factor B (CFB), complement C1r (C1R), C1R-like, C3aR1, complement factor properdin (CFP) and complement factor I (CFI) were upregulated two- to 10.6-fold in response to the infection." (PMID 41398915, 2025). "In addition, the expression of c1ql2, C3, C5, C7, C9, CFB, and complement factor H (CFH) was regulated in rainbow trout stimulated with β-glucan upon infection with A. salmonicida, suggesting improved immune enhancement." (PMID 34835165, 2021). "Interestingly, here, we saw increased complement factor B in the absence of a true infection as only the viral proteins are expressed, suggesting that the proteins themselves are an inflammatory stimulus." (PMID 27378953, 2016). "When complement factor B was considered, Control AMs did not produce detectable amounts of the molecule, but as for C3, ΔLasB-PAO1 infection upregulated that factor, albeit to lesser levels (from 0 to 3 ng/mL)." (PMID 30083156, 2018).
tumor (37 papers, 2014 to 2026). "Mutations in the CFB gene result in reduced activation of B cells, which in turn lead to changes in the tumor immune environment." (PMID 40496561, 2025). "Mutations in the CFB gene lead to reduced activation of B cells, which in turn leads to changes in the tumor’s immune environment." (PMID 40496561, 2025). "Our data indicate that CFB, a key secreted protein, promotes proliferation by preventing cellular senescence and is associated with immunological tumor promotion in PDAC." (PMID 34075561, 2021). "CFB, C3, and C5 are commonly associated with changes in the tumor microenvironment." (PMID 37628784, 2023). "Our results demonstrate the upregulation of C1R, C1S, C3, IGHM and CFB in poorly differentiated tumours, suggesting activation through the classical pathway." (PMID 40847563, 2025). "It demonstrated a notably elevated expression of SERPINA1, RASGRP1, and CFB in tumor tissues, while C1S and TLN2 showed significantly higher expression in normal tissues." (PMID 38751445, 2024). "Secreted from the tumor cells CFB protein correlated with increases of immunosuppressive cells, including Tregs, MDSCs and TAMs." (PMID 35860237, 2022). "CFB affects the control of tumor growth, and the activation of the lectin pathway was increased significantly in patients with CRC compared to healthy subjects." (PMID 34589434, 2021). "Immunofluorescence staining revealed a correlation between stromal CFB expression in the tumor microenvironment and an enrichment of immunosuppressive regulatory T-cells (Tregs), myeloid-derived suppressor cells (MDSCs) and tumor-associated macrophages (TAMs)." (PMID 34075561, 2021). "mRNA expression of SAA2 was similar in healthy and tumor samples, but CFB was significantly more expressed in tumor samples." (PMID 34670568, 2021). "We found that CFB was primarily expressed in the stroma surrounding the tumor and in the cytoplasm of tumor cells." (PMID 34075561, 2021). "We found that CFB was highly expressed in primary tumor samples compared to adjacent normal pancreatic tissues." (PMID 34075561, 2021). "Collectively, our results suggest that CFB secreted from tumor cells leads to a bypass of senescence and fosters cooperation between tumor cells and pro-tumoral immune cells in favor of PDAC progression." (PMID 34075561, 2021). "Complement Factor B (CFB) is one of the factors of the complement system, and after interacting with the tumor cell lines MDA-MB231, CFB can show significant upregulation." (PMID 33193731, 2020). "Increased expression of CFB by tumor cells in cSCC in vivo was detected and there was a correlation between the expression of CFB and tumor progression and aggressiveness in cSCCs in vivo." (PMID 31331124, 2019). "The expression of CFB was limited to the cytoplasm of the basal and suprabasal layers of the normal oral tissue, whereas broad positivity was found in the tumor cells." (PMID 26540631, 2015). "Indeed, macrophage depletion via anti-CSF1R mAb or clodronate liposomes significantly decreased the number of cells expressing CXCL1/2 and CFB in tumor, as well as the levels of C3a and C5a." (PMID 41480760, 2026). "The expression of CXCL1/2 or CFB was markedly elevated in macrophages that had engulfed GFP+ tumor." (PMID 41480760, 2026). "CFB can also suppress tumor development by negatively regulating the Ras/MAPK signaling pathway." (PMID 40496561, 2025). "For PDAC, a tumor-promoting activity was found for complement factor B (fB)." (PMID 36547187, 2022). "Using in vitro co-cultures of breast and prostate cancer cells with lymphatic endothelial cells (LEC), Oliveira-Ferrer demonstrated tumor-dependent induction of C3, CFB and C1q secretion as well as that chemokine upregulation (CCL7, CXCL6, CXCL1) by the LECs promotes tumor metastasis." (PMID 35860237, 2022). "CFB mediated protection from senescence of tumor cells and cell proliferation." (PMID 35860237, 2022).
tumor (continued). "Recent study has found that complement factor B (CFB) could promote proliferation by preventing cellular senescence and had profound implication in immunological tumor promotion in PC." (PMID 36518628, 2022). "Similarly, the highest expression of C2orf27A and IGF2R was found at tumor grade 3, and the lowest expression of CFB and PON1 was found at grade 4." (PMID 33495404, 2021). "In particular, CFB accelerates tumor invasion and migration." (PMID 28394947, 2017). "Furthermore, CFB is a protein that is secreted by macrophages, fibroblasts, endothelial cells and tumor cells." (PMID 26540631, 2015). "Therefore, we evaluated the paracrine effect that CFB depletion in tumor cells could exert on macrophage chemotaxis." (PMID 26540631, 2015). "To evaluate the importance of CXCL1/2 and CFB in driving NET formation under treatments, we applied Dox in combination with SB225002 or LNP023, the inhibitors of CXCR2 (the co-receptor of CXCL1/2) or CFB, respectively, in orthotopic 4T1 and MCF-7 tumor model." (PMID 41480760, 2026). "In contrast, CytoB reduced phagocytosis of macrophages cocultured with tumor debris and decreased the induction of CXCL1/2 and CFB expression in macrophages." (PMID 41480760, 2026). "As expected, pretreatment of human peripheral monocyte-derived macrophages with UNC2250 decreased tumor cell debris–induced elevation of CXCL1/2 and CFB, suggesting that increased engulfment of tumor debris promoted CXCL1/2 and CFB production." (PMID 41480760, 2026). "As expected, macrophage engulfment of debris, tumor growth, NETosis, and CXCL1/2 and CFB expression were obviously reduced in the presence of UNC2250." (PMID 41480760, 2026). "Mechanistically, macrophage-engulfed cathepsin C (CTSC) from tumor debris activates TLR4/NF-κB signaling, upregulating CXCL1/2 and complement factor B (CFB) to drive neutrophil recruitment and NET formation." (PMID 41480760, 2026). "Specifically, patients with tumours exhibiting high expression of ECM‐related (SPP1 and MUC5B) and complete active related genes (CFB and CCL20) in either the epithelial or macrophage compartment had significantly shorter disease‐free survival (DFS)." (PMID 40847563, 2025). "We have also reported that complement factor B (CFB) secreted by PDAC cells regulates senescence, leading to the promotion of tumour progression within the TME of PDAC." (PMID 41044172, 2025). "Specifically, tumor tissues show increased expression of SERPINA1, RASGRP1, and CFB compared to normal tissues, whereas C1S, SERPINF2, and TLN2 display the opposite pattern." (PMID 38751445, 2024). "In the three GEO datasets, the expression of CFB and PPP1R18 was significantly higher in tumor samples, whereas that of TOM1L1 was significantly lower." (PMID 36611973, 2023). "In the ICGC dataset, CFB and PPP1R18 were significantly upregulated in tumor samples, whereas TOM1L1 was significantly downregulated in tumor samples." (PMID 36611973, 2023). "Compared to nondistant metastatic ccRCC tissues and normal tissues, the expression patterns of CFB and PPP1R18 were significantly higher in distant metastatic ccRCC samples and tumor samples, whereas the expression of TOM1L1 was significantly lower." (PMID 36611973, 2023). "An increased expression of FCGBP, BPIFB, F5, CST1, and CFB and their correlation to epithelial-to-mesenchymal transition (EMT) under clinorotation were detectable as potential tumor suppressor biomarkers." (PMID 37048115, 2023). "Six sEV proteins were identified, namely, GCLM, KEL, APOF, CFB, PDE5A, and ATIC, which properly distinguished normal control, early neoplasia, and advanced neoplasia patients from each other." (PMID 34589434, 2021). "In line with this idea, we found that CFB co-localizes with tumor infiltrating immunosuppressive cells, resulting in cancer progression despite the presence of CD8+ tumor infiltrating lymphocytes in the TME of PDAC tissues." (PMID 34075561, 2021).
tumor (continued). "Complement components that were most frequently upregulated in tumor tissues were CD46, C2 and complement factor B (CFB)." (PMID 33628739, 2020). "The protein CTSC in tumor debris induces CXCL1/2 and CFB expression." (PMID 41480760, 2026). "Our data indicated that blockade of CXCR2 or CFB efficiently prohibited Dox-induced NET generation and enhanced chemotherapy effects, leading to markedly decreased tumor growth." (PMID 41480760, 2026). "Phagocytosis of tumor debris by macrophages contributes to CXCL1/2 and CFB elevation and NETosis." (PMID 41480760, 2026). "Mechanistically, the cathepsin C in tumor debris generated by anticancer therapy is phagocytosed by macrophages and drives CXCL1/2 and complement factor B production via activating the TLR4/NF-κB signaling pathway, subsequently promoting NETosis and impairing therapeutic efficacy." (PMID 41480760, 2026). "No significant results were observed between the tumour grade and immunohistochemical expression of Claudin-15 and CFB." (PMID 37761312, 2023). "Interestingly, we observed increased expression of FCGBP, BPIFB, F5, CST1, and CFB and their correlation to EMT under SMG, rendering them potential tumor suppressor biomarkers." (PMID 36613598, 2022). "The result showed that the lower mRNA expressions of C3, C5, CFB, and CLU were correlated with more advanced cancer stage, while the lower mRNA expressions of C1S, C8B, CFI, MBL2, and C4BPA were correlated with higher tumor grade in HCC patients." (PMID 34813686, 2022). "The present study identified six sEV proteins, namely, GCLM, KEL, APOF, CFB, PDE5A, and ATIC, that could distinguish early neoplasia, advanced neoplasia, and normal controls from each other well." (PMID 34589434, 2021). "We next measured SAA2 and CFB levels in plasma samples from patients with (M1) or without metastases (M0), collected before or after surgical resection of the primary tumor." (PMID 34670568, 2021). "The results of ELISA and qRT-PCR assay revealed that tumor debris stimulation and engulfment remarkably elevated the expression of CXCL1/2 and CFB in mouse bone marrow–derived macrophages (BMDMs), whereas intact tumor cell treatment exerted less effect on CXCL1/2 or CFB production." (PMID 41480760, 2026). "To exclude the confounding effects induced by primary tumor, we constructed lung or liver experimental metastasis models by injecting 4T1 cells via tail vein or EO771 cells intrasplenically and applied Dox with or without CXCR2 or CFB inhibition." (PMID 41480760, 2026).
cancer (17 papers, 2014 to 2026). A tumor composed of atypical neoplastic, often pleomorphic cells that invade other tissues. "Our in vitro data indicate that CFB plays a functional role in PDAC cancer cell survival by preventing cellular senescence via p21 expression regulation." (PMID 34075561, 2021). "IHC staining clearly showed high CFB expression in both cancer cells and stroma of resected human PDAC tissues." (PMID 34075561, 2021). "We finally examined correlations between CFB expression and the presence of pro-tumoral immune cells, promoting cancer cell spread and distant metastasis in human PDAC tissues." (PMID 34075561, 2021). "The normalized areas were statistically analyzed by our paired setup and the higher abundance in cancer samples were confirmed to pyruvate kinase, alpha-2-macroglobulin, and complement factor B (p-value < 0.05)." (PMID 30999875, 2019). "Ceruloplasmin, Complement factor B or complement component C3 had already been reported elevated in hepatocarcinoma and other cancers." (PMID 25826090, 2015). "Further experiments aimed at the regulation of senescence by CFB may underscore the context-dependent effects of senescence, including the potential involvement of the senescence-associated secretory phenotype (SASP) in cancer progression." (PMID 34075561, 2021). "Moreover, in line with the results of chemotherapy, the expression of CXCL1/2 and CFB in macrophages was significantly increased in response to local radiation, evidenced by data from immunofluorescence, Western blot, scRNA-Seq, and ELISA in mouse cancer models." (PMID 41480760, 2026). "This was also verified by orthotopic MCF-7 cancer model and spontaneous MMTV-PyMT FVB/NJ mouse model, where Dox treatment obviously stimulated the production of CXCL1/2 and CFB from tumoral macrophages." (PMID 41480760, 2026). "Among the 19 cancer types, PPP1R18/KIAA1949 (p = 2.98 × 10−32) and TOM1L1 (p = 3.87 × 10−30) exhibited the highest specificity for KIRC/ccRCC, and CFB also presented excellent specificity for KIRC/ccRCC (p = 3.76 × 10−13)." (PMID 36611973, 2023). "Thus, we further examined these genes and found that the mRNA expressions of C3, C5, CFB, and CLU were correlated with cancer stage and prognosis in patients with HCC." (PMID 34813686, 2022). "In addition to the role of FCGBP and BPIFB, the complement factor B (CFB) and the chimeric tumor suppressor 1 (CST1) are shown to exert protective roles in cancer." (PMID 36613598, 2022). "Since CFB plays a crucial role in activation of the C3-C5 cascade in the alternative pathway, we hypothesized that CFB may be governed by PDAC cancer cells and act on the immunosuppressive response orchestrated by Tregs, MDSCs and TAMs in the TME." (PMID 34075561, 2021). "Genes positively correlated with purity showed enrichment in cancer-related pathways and processes such as epithelial-mesenchymal transition (BASP1, COL4A1, THBS2), genes involved in the TNFA signaling via NFKB (SPSB1, SMAD3), and genes upregulated by KRAS activation (CFB, MAFB)." (PMID 37041233, 2023). "In addition, both CFB and C3 have not been previously reported to be related to cancer biomarkers, according to the IPA biomarker analysis and The Human Protein Atlas." (PMID 26540631, 2015).
kidney disease (8 papers, 2021 to 2026). "Several peptides derived from the complement proteins C3, C4 and CFB were found significantly associated with specific kidney disease etiologies." (PMID 34941814, 2021). "Complement factor B (FB) mutant variants are associated with excessive complement activation in kidney diseases such as atypical hemolytic uremic syndrome (aHUS), C3 glomerulopathy and membranoproliferative glomerulonephritis (MPGN)." (PMID 34177949, 2021). "Several C3- and CFB-derived peptides were also associated with specific kidney disease etiologies." (PMID 41752115, 2026). "Proteins CFB, С3, C4A, and C4B are associated with the development of kidney diseases." (PMID 39896931, 2024).
cardiovascular disease (5 papers, 2013 to 2024). "CFB is elevated in adipose tissue and serum of patients with DM and cardiovascular disease, and abundantly expressed in inflamed adipose tissue." (PMID 34462518, 2021). "For example, the ADIPOQ, AMY1A, CFB, HP and HBB are associated with the metabolic diseases, while the FBP4, HP, LPL and MYL2 are related to the cardiovascular diseases." (PMID 24204599, 2013). "Moreover, recent research suggests the overexpression of CFB may serve as a prognostic indicator of severe viral lung disease, such as that of SARS-CoV-2 infection or cardiovascular disease." (PMID 39346910, 2024).
retinopathy (4 papers, 2013 to 2023). "Specifically, polymorphisms in CFB have been associated with nAMD and retinopathy." (PMID 34502486, 2021). "Also, RP1L1, PROM1, CRX, CFI and CFB, and KCNJ13 have been linked to retinopathy." (PMID 33330132, 2020).
bacterial infections (3 papers, 2014 to 2025). "Similarly, mice deficient in CFB develop normally but lack AP activity and are more susceptible to bacterial infections." (PMID 40028332, 2025).
genetic disorders (1 paper, 2012). "In this study, we found that in 45 children diagnosed with aHUS, genetic disorders in complement-regulating genes encoding CFH, CFI, MCP, CFB, C3, and THBD, as well as the presence of αFH with or without a homozygous deletion in CFHR1/3, are linked with clinical presentation, treatment, and outcome." (PMID 22410797, 2012).
immune disease (1 paper, 2021). "In KEGG, genes associated with immune disease and system include HLA-DQA1, HIST1H2BL, HIST1H2AL, C2, CFB, HSPA1A, TAP2, HIST1H3Jand ATP6V1G2." (PMID 34367251, 2021).
inflammation (1 paper, 2014). Aberrant reaction of the microcirculation characterized by movement of fluid and leukocytes from the blood into extravascular tissues. "The genes BMP6, CFB and MYLK have previously been associated with airway inflammation and hyperresponsiveness." (PMID 24475887, 2014).
respiratory disease (1 paper, 2025). "In cattle, CFB expression correlates with clinical signs of respiratory disease, supporting its potential as a biomarker." (PMID 41144480, 2025).
CFB also shares sentences with these, for which no sentence is quoted: ovarian carcinoma (3 papers); adenocarcinoma (2); allergic rhinitis (2); atherosclerosis (2); chronic renal diseases (2); Crohn disease (2); diabetic retinopathy (2); gastric cancer (2); glioma (2); glomerulosclerosis (2); hyperlipidemia (2); osteoporosis (2); rheumatoid arthritis (2); acne (1); adenoma (1); age (1); alcohol addiction (1); amyloidosis (1); Angina (1); Anophthalmia (1); Atrophy (1); autoimmune disease (1); autosomal dominant polycystic kidney disease (1); babesiosis (1); Behçet’s disease (1); bipolar disorder (1); cardiopulmonary diseases (1); cerebral toxoplasmosis (1); chronic pancreatitis (1); Cirrhosis (1).
A further 60 diseases each share a sentence with CFB in 1 paper.